OR13C5 (olfactory receptor family 13 subfamily C member 5)
Description:
Odorant receptor.
Synonyms: OR9-11
Tractability: Antibody: its Gene Ontology location is reachable by antibodies, with high confidence; UniProt places it where antibodies can reach, with medium confidence; UniProt predicts a signal peptide or a membrane-spanning region; the Human Protein Atlas places it where antibodies can reach.
Gene: Protein-coding gene on chromosome 9 (104,598,457 to 104,599,413, reverse strand). Ensembl gene ENSG00000277556.
Subcellular location: Cell membrane
Subcellular location (Human Protein Atlas): Plasma membrane; Nucleoplasm
Pathways (Reactome):
Sensory Perception: Expression and translocation of olfactory receptors
Gene Ontology:
Molecular function: olfactory receptor activity; G protein-coupled receptor activity
Biological process: detection of chemical stimulus involved in sensory perception of smell; G protein-coupled receptor signaling pathway
Cellular component: plasma membrane; membrane
Genetic constraint (gnomAD): Loss-of-function variants: 9 observed, 12.53 expected, observed/expected ratio (o/e) 0.72, 90% interval 0.43 to 1.25. The upper end of that interval is the gene's LOEUF score, 1.25, which puts it in group 5 of 6, group 1 being the genes least tolerant of losing a copy. Missense variants: 343 observed, 358.91 expected, observed/expected ratio (o/e) 0.96, 90% interval 0.87 to 1.04. Synonymous variants: 120 observed, 126.95 expected, observed/expected ratio (o/e) 0.95, 90% interval 0.81 to 1.1.
Homologues: Orthologues: chimpanzee OR13C5 (97% identical), dog OR13C2B (86% identical), dog OR13C2 (86% identical), rat Or13c9 (76% identical). Paralogues in human: OR13C2 (93% identical), OR13C9 (86% identical), OR13C4 (64% identical), OR2S2 (64% identical), OR13C3 (63% identical), OR13C8 (62% identical), OR13D1 (58% identical), OR2K2 (54% identical), OR13J1 (49% identical), OR2F1 (46% identical), OR2F2 (45% identical), OR2G3 (45% identical), and 80 more.
Diseases named in the same sentence as OR13C5 in open-access papers:
OR13C5 is named in the same sentence as 4 diseases in open-access papers, as found by Europe PMC text mining. Sharing a sentence is not in itself a finding about the gene and the disease.
OR13C5 shares sentences with these, for which no sentence is quoted: pancreatic cancer (2 papers); glioblastoma (1); lung carcinoma (1); tumor (1).